GCG (glucagon)
Diseases named in the same sentence as GCG in open-access papers (continued):
Sharing a sentence is not in itself a finding about the gene and the disease.
Hyperglycemia (continued). "These subjects can have disproportionally amplified hepatic glucose output, likely due to reduced sensitivity in the physiological suppression of glucagon production by hyperglycemia and/or GLP-1." (PMID 26038839, 2015). "This reduction in hyperglycemia was associated with a 70% reduction in plasma corticosterone and ACTH concentrations but occurred independently of any change in plasma insulin, glucagon, epinephrine, norepinephrine or growth hormone concentrations." (PMID 25916467, 2015). "Consistent with ATP’s controlling glucagon and insulin secretion during hypo- and hyperglycemia, respectively, the dose-response relationship for glucose-induced [ATP]pm generation was left shifted in α-cells compared to β-cells." (PMID 25911612, 2015). "DPP-4 regulates the activity of the secretory hormones GLP-1 and GIP to maintain glucose homeostasis (enhanced insulin secretion and glucagon suppression), thereby improving postprandial and fasting hyperglycaemia." (PMID 26075286, 2015). "The improvement of glycemic variability by vildagliptin was probably related to its mechanism of action: to reduce glucagon at hyperglycemia and sustain glucagon counterregulation." (PMID 26587020, 2015). "Ex-4 is an antidiabetic agent, which reduces hyperglycemia through increased glucose-dependent insulin secretion, glucagon suppression, delayed gastric emptying and appetite suppression." (PMID 25625935, 2015). "We found that the alteration of Mio and additional proof-of-concept candidates, such as glycolysis genes, MODY homologues, insulin (Dilp) and glucagon (Akh), all produced hyperglycaemia in a manner predicted from mammalian studies." (PMID 25994086, 2015). "Exaggerated and dysregulated glucagon secretion can exacerbate hyperglycemia contributing to type 2 diabetes (T2D)." (PMID 26075596, 2015). "GLP-1 decreases blood glucose levels during hyperglycemia by stimulating insulin secretion and reducing glucose-dependent glucagon secretion." (PMID 26366173, 2015). "Under these pathological conditions, high glucose levels fail to suppress glucagon release, favoring higher plasma glucagon levels, which promote hepatic glucose output and contribute to hyperglycemia." (PMID 24705399, 2014). "Mice lacking microRNA-375 (375KO) share some characteristics with our DEX rats (e.g., hyperglycemia, fast and fed hyperglucagonemia, glucose intolerance and reduced effect of glucose to inhibit glucagon secretion)." (PMID 24705399, 2014). "Taken together, the data confirm that cells with a β-cell lineage express glucagon in response to chronic hyperglycaemia by increasing expression of α-cell transcription factors." (PMID 25145789, 2014). "We demonstrate that glucagon plays a key role in steroid-induced hyperglycemia, as alterations in pancreatic α-cell function led to fasting and fed hyperglucagonemia." (PMID 24705399, 2014). "Previous data with the same antagonist have showed its inability to activate glycogenolysis as well as its ability to lowers the hyperglycemia produced by endogenous glucagon in streptozotocin diabetic rats." (PMID 24705399, 2014). "Taken together, our data provide evidences that GPR40 activation can suppress glucagon secretion under pathologically relevant condition thus providing potential benefit in reducing hyperglycemia." (PMID 25186493, 2014). "We have previously shown that there is a significant hyperglycemia after orthopedic trauma in OZ despite decreased plasma glucagon levels." (PMID 25472607, 2014). "In T2DM patients, impaired beta cell insulin secretion and impaired suppression of glucagon secretion from alpha cells lead to hyperglucagonemia mediated hyperglycemia." (PMID 25186493, 2014). "Hyperglycemia stimulates secretion of insulin and amylin, reducing the secretion of glucagon; it also decreases the secretion of ghrelin, which reduces gastric emptying, via parasympathetic signal." (PMID 25003936, 2014).
Hyperglycemia (continued). "Hyperglucagonemia and abnormal insulin-to-glucagon ratios observed in subjects with T2D contribute to pathologic hyperglycemia in both postabsorptive and fasting states by increasing hepatic glucose production." (PMID 23226550, 2012). "In the acute stress response, neuroendocrine stimulations with high levels of glucagon, catecholamines, glucocorticoids, and proinflammatory cytokines are important factors leading to hyperglycemia." (PMID 23056354, 2012). "It is well known that impaired α-cell function can lead to excessive glucagon release during postabsorptive and fasting states, which contributes to the development and progression of hyperglycemia." (PMID 23226550, 2012). "There has thus been considerable interest in the development of therapeutic interventions that would ameliorate hyperglycemia by reducing circulating levels of glucagon or inhibiting glucagon actions in target tissues." (PMID 23185367, 2012). "Not only is there insulin resistance in T2DM, but there is also a loss of the early phase insulin secretion leading to persistent hyperglycemia secondary to the inability to suppress both glucagon secretion and hepatic glucose output." (PMID 23198247, 2012). "While the treatment and management of hyperglycemia especially in T2D has always been based on insulin response, emerging evidence suggests that inhibition of glucagon signalling presents a potential approach to the maintenance of normal glucose levels." (PMID 22046328, 2011). "Biguanides (e.g. metformin) have limited efficacy to lower hyperglycemia and exert their effects by decreasing carbohydrate absorption from the intestine, hepatic gluconeogenesis and glucagon secretion from the pancreas." (PMID 23493930, 2011). "Concerning the glucose metabolism, excess glucagon secretion, abnormally accelerated gastric emptying during hyperglycemia, obesity, and increased food intake all contribute to hyperglycemia." (PMID 20470376, 2010). "Excess glucagon secretion, abnormally accelerated gastric emptying during hyperglycemia, obesity, and increased food intake all contribute to hyperglycemia." (PMID 19619327, 2009). "Interestingly, exogenous GLP-2 has been reported to increase glucagon levels during euglycemia and hyperglycemia in the isolated rat pancreas and in humans, supposedly via direct stimulation of GLP-2 receptors on pancreatic α cells." (PMID 41541287, 2026). "Whereas short-acting GLP1RAs suppress postprandial hyperglycemia mainly by delaying gastric emptying, long-acting GLP1RAs such as dulaglutide and liraglutide lower fasting and postprandial BS by enhancing insulin secretion and reducing glucagon secretion." (PMID 41347115, 2026). "Small increases in α-cell glucagon secretion normally occur at mealtimes, which augment insulin secretion from surrounding β cells; however, excess postprandial glucagon secretion in T2D can worsen hyperglycemia by increasing hepatic glucose production." (PMID 41502124, 2026). "Osteoclasts are also involved in influencing systemic metabolism through secreted factors, such as dipeptidylpeptidase-4 (DPP4), which reduces GLP-1 levels, leading to decreased insulin, increased glucagon secretion, and hyperglycemia, linking bone remodeling to energy homeostasis." (PMID 41559024, 2026). "Additionally, glucagon-driven amino acid breakdown can lead to muscle wasting, providing substrates for gluconeogenesis and thereby further maintaining hyperglycemia." (PMID 40822953, 2025). "Moreover, α cells exposed to hyperglycemia showed that glucagon degradation at LAMP2+ lysosomes is reduced, with increased redirection to secretory LAMP1+ lysosomes." (PMID 41026524, 2025). "The general pathophysiology of diabetic ketoacidosis (DKA) involves severe insulin deficiency and an increase in insulin-antagonist hormones such as glucagon, leading to hyperglycemia because of impaired glucose utilization and increased ketone body production from excess lipolysis." (PMID 40951123, 2025).
Hyperglycemia (continued). "GLP-1, upon its binding to its receptors on pancreatic β-cells, stimulates insulin release in a glucose-dependent manner, while concurrently inhibites glucagon release from pancreatic α-cells during hyperglycemia, thereby contributing to lower fasting and postprandial blood glucose levels." (PMID 40722592, 2025). "However, the combined effect of insulin resistance and elevated counter-regulatory hormones, such as glucagon, cortisol, and catecholamines, promotes glucose mobilization and downstream hyperglycemia." (PMID 39913488, 2025). "In patients with hyperglycemia treated with insulin, glucagon excess contributes—at least in part—to poor glycemic control and may therefore be targeted through inhibition of glucagon secretion or action." (PMID 41149695, 2025). "By combining automated delivery of glucagon alongside insulin, these systems aim to not only correct hyperglycaemia but also prevent or rapidly correct hypoglycaemia, something that insulin-only systems inherently struggle with due to the delayed pharmacokinetic profile of insulin analogues." (PMID 40718205, 2025). "Hyperglycemia, and subsequently compensatory hyperinsulinemia, can lead to a release of autonomic counterregulatory hormones, such as cortisol, adrenaline, growth hormone, and glucagon, which are involved in insomnia." (PMID 39716153, 2024). "High levels of glucagon are seen as a major contributor to hyperglycemia." (PMID 38970008, 2024). "We hypothesize that glucagon is an important mediator in explaining both hyperglycemia at short term and the normalization of blood glucose levels at three weeks after CSD." (PMID 39462137, 2024). "Exenatide reduces the concentration of glucagon in the blood during periods of hyperglycemia." (PMID 39598478, 2024). "We reasoned that the effect of pramlintide cotreatment to lower serum glucagon:insulin ratio could be used alongside lower doses of liraglutide to enhance protection from olanzapine-induced hyperglycemia and enable lower doses of drugs to be used." (PMID 38188526, 2024). "However, these islets exhibited a significant elevation in fasting glucagon secretion which likely contributes to the fasting hyperglycemia." (PMID 38700926, 2024). "Suppression of glucagon hypersecretion can normalize hyperglycemia during type 1 diabetes (T1D)." (PMID 38258903, 2024). "Therefore, therapeutic approaches that target the reduction of glucagon levels or inhibiting its downstream effects are of paramount importance in the management of hyperglycemia in individuals with T2DM." (PMID 39193349, 2024). "Accordingly, a glucagon-centric hypothesis proposes that combating hyperglucagonemia can result in normalization of hyperglycemia in T1D." (PMID 38258903, 2024). "Dysregulation of α-cell glucagon secretion contributes to hyperglycemia present in T1D and T2D." (PMID 38326874, 2024). "Furthermore, GLUT-2 is associated with glucagon release suppression, as revealed by a study on GLUT-2 knockout mice, where significant hyperglycemia was observed." (PMID 38333863, 2024). "Blocking the action of glucagon with a monoclonal antibody of GCGR (Ab-4) improved hyperglycemia." (PMID 39120275, 2024). "GLP1-RAs are incretin medications that increase the production of glucose-dependent insulin, suppress the release of glucagon from pancreatic α cells in hyperglycemia states, diminish the stomach’s emptying, and affect appetite, resulting in a decrease in food consumption." (PMID 39768947, 2024). "The patients have hyperglycemia due to abnormal glucagon release from pancreatic α-cells." (PMID 39493778, 2024). "The glucagon response to arginine (measured as the maximum glucagon concentration after the stimulus) was significantly lower during hyperglycemic phase (P < 0.001) compared with the euglycemic phase, and during hyperglycemia combined with GLP1 (P < 0.001) compared with only hyperglycemia." (PMID 38446636, 2024).
Hyperglycemia (continued). "Diabetic patients with surgical co-morbidity may experience stressful hyperglycemia due to increased glucagon (glucocorticoids) levels in the body." (PMID 38724646, 2024). "Thus, in T2D patients, β cells are exposed to two counteracting stimuli, glucagon‐induced hepatic glucose production, and hyperglycemia stimulation, whereas KP production inhibits glucose‐stimulated insulin secretion." (PMID 38599822, 2024). "An inappropriate postprandial inhibition of glucagon-secreting α-cells strengthens hyperglycemia." (PMID 39519472, 2024). "The most relevant CpG site (cg14671384, P = 9.09 × 10–9) locates in the promoter of the SLC38A4 gene (Solute Carrier Family 38 Member 4), which has been reported to be a transporter of cationic and neutral amino acids and closely related with glucagon and hyperglycaemia." (PMID 38802969, 2024). "Nickel has been shown in animal studies to induce hyperglycemia, glucagon, and insulin resistance." (PMID 39564359, 2024). "In some patients with CD and acromegaly, the resulting imbalance between insulin and glucagon may lead to pasireotide-induced hyperglycemia." (PMID 39735646, 2024). "Moreover, GLP-1 has a direct impact on pancreatic β-cells within the islets of Langerhans, stimulating insulin secretion and reducing glucagon release, which collectively helps to maintain glucose homeostasis and protect against postprandial hyperglycemia." (PMID 39518431, 2024). "Our findings have significant implications for understanding the pathophysiology of postprandial hyperglycemia in T1D and may provide the development of glucagon-based therapies for this condition." (PMID 39149119, 2024). "In prolonged hyperglycemia, the balance between glucagon and insulin action weakens." (PMID 39566886, 2024). "Several reports suggest that relative hyperglucagonemia contributes to fasting and postprandial hyperglycemia in T2D, and glycemic control may be achieved by blocking glucagon action." (PMID 39594592, 2024). "In addition, most of the innovation in the glucagon field was focused on developing novel glucagon receptor antagonists for the treatment of T2D, due to the impact of glucagon on hepatic glucose production and hyperglycemia." (PMID 38477666, 2024). "In ZDF rats, during phase II when basal hyperglycemia was restored with GCG-ZDF-BC and INS-ZDF-BC, EGP and TGO tended to reduce progressively by 13% (−Δ 7.3 μmol·kg−1·min−1) and 7% (−Δ 6.6 μmol·kg−1·min−1), respectively, with a slight decrease in the EGP fraction contributing to TGO from 66% to 62%." (PMID 38265288, 2024). "The presence of lectins, β-glucans, polyphenols, p-hydroxybenzoic acid, protocatechuic acid, agllic acid, cinnamic acid, p-coumaric acid, ferulic acid, chlorogenic acid, and catechin in mushrooms improves hyperglycemia by regulating insulin and glucagon secretion." (PMID 39519546, 2024). "The authors concluded that alpha-cell dysfunction in youth does not appear to explain the observed beta-cell hyperresponsiveness and insulin-resistance while elevation of glucagon (fasting and postprandial) has been suggested to drive hyperglycemia in other studies." (PMID 39027470, 2024). "Additionally, arginine stimulates glucagon production, which exacerbates hyperglycemia and acidosis in DKA." (PMID 39707182, 2024). "All GLP-1 RAs function similarly by enhancing insulin secretion in response to hyperglycemia, inhibiting glucagon secretion under hyperglycemic or euglycemic conditions, slowing gastric emptying to mitigate postprandial glucose spikes, and promoting weight loss by reducing calorie intake." (PMID 39720384, 2024). "Thus, in the framework of our CSD-paradigm, we anticipate an approximately one week delay between expected glucagon surges -due to acute stress- and evident hyperglycemia." (PMID 39462137, 2024). "Insulin corrects hyperglycemia and ketone production, and it inhibits glucagon and lipolysis." (PMID 39360087, 2024).
Hyperglycemia (continued). "Hyperglycemia triggers β-cell insulin release and suppression of α-cell glucagon secretion." (PMID 39619323, 2024). "First, stress associated with critical illness is characterized by activation of the hypothalamic‒pituitary‒adrenal (HPA) axis and increased release of glucocorticoids, epinephrine, glucagon, and growth hormone, which can lead to the occurrence of stress hyperglycemia." (PMID 38725059, 2024). "In pancreatic dysfunction, the release of insulin/glucagon is impaired, leading to hyperglycemia." (PMID 36900540, 2023). "Therefore, GLP-1 protects against hyperglycaemia by enhancing insulin secretion and inhibiting glucagon secretion." (PMID 37237989, 2023). "Hyperglycemia was found to disrupt the function of HIF-1 inhibitors (berberine and HIF-1 small interfering RNA (siRNA)), which confirmed the involvement of HIF-1 associated signaling pathway in glucagon-induced hyperglycemia." (PMID 36984785, 2023). "Consequently, treatment with pasireotide has been associated with significant inhibition of insulin and incretins secretion, along with only a modest suppression of glucagon levels, which commonly leads to pasireotide-induced hyperglycemia." (PMID 37139336, 2023). "High glucagon levels increase hepatic glucose output and contribute to hyperglycemia." (PMID 36732571, 2023). "Consistently, acute IP injection of galanin also caused hyperglycemia in wild-type (WT), but not Gcg−/− mice, indicating a glucagon-dependent role." (PMID 37221172, 2023). "The action of CRV on hyperglycemia, detected with our approach, may be due to its action on adrenaline, glucagon, or corticosterone secretion, which may directly affect the enzymes involved in glycogenolysis and/or the gluconeogenesis pathway." (PMID 37631083, 2023). "Recently, Albrechtsen et al15 observed that acute administration of ARNIs in T2DM patients may not depend on the alterations of enteropancreatic hormones, and NEP inhibitors may lead to hyperglycemia due to an increment in glucagon serum levels." (PMID 37078106, 2023). "Elevated glucagon levels were considered to be a significant factor in hyperglycemia." (PMID 37563588, 2023). "However, the acute effect of NEP inhibitors leads to postprandial hyperglycemia by increasing glucagon levels." (PMID 37078106, 2023). "Therefore, prolonged hyperglycaemia can also affect the GABA-mediated β-cell paracrine control of glucagon secretion." (PMID 37159865, 2023). "However, with the development of impaired glucose tolerance and T2DM, glucagon continues to induce glucose production during hyperglycemia in fasted and preprandial conditions." (PMID 37764697, 2023). "In T2D, glucagon hypersecretion contributes to hyperglycemia." (PMID 36686477, 2022). "Hyperglycemia and insulin resistance affect metabolic abnormalities and the immune function of the cellular components of the innate immune system by releasing cortisol, catecholamines, cytokines, glucagon, and growth hormone." (PMID 35079646, 2022). "Thus, the transition from preclinical to clinical T1D is marked by progressive loss of β-cells with attendant inability of β-cells to suppress glucagon-mediated hyperglycemia." (PMID 35592786, 2022). "Ground-breaking work from Roger Unger and colleagues showed that the disruption of the glucagon-insulin bi-hormonal relationship may contribute to hyperglycemia in the diabetic condition." (PMID 35547006, 2022). "Work characterizing the phenotype of Gcgr knockout mice and various therapeutic modalities targeting the glucagon-GCGR system to lower glucose in an array of preclinical rodent models produced results that supported discovering agents to block glucagon action as a way to reduce hyperglycemia." (PMID 35547006, 2022). "Paradoxical glucagon secretion under hyperglycemia is frequently observed in diabetic patients." (PMID 35121731, 2022). "Thus, with prolonged hyperglycemia, the insulin+ cells were reduced, and instead, the glucagon+ cells increased." (PMID 35203411, 2022).